HLA-B (major histocompatibility complex, class I, B)
Description:
Antigen-presenting major histocompatibility complex class I (MHCI) molecule. In complex with B2M/beta 2 microglobulin displays primarily viral and tumor-derived peptides on antigen-presenting cells for recognition by alpha-beta T cell receptor (TCR) on HLA-B-restricted CD8-positive T cells, guiding antigen-specific T cell immune response to eliminate infected or transformed cells. May also present self-peptides derived from the signal sequence of secreted or membrane proteins, although T cells specific for these peptides are usually inactivated to prevent autoreactivity. Both the peptide and the MHC molecule are recognized by TCR, the peptide is responsible for the fine specificity of antigen recognition and MHC residues account for the MHC restriction of T cells. Typically presents intracellular peptide antigens of 8 to 13 amino acids that arise from cytosolic proteolysis via constitutive proteasome and IFNG-induced immunoproteasome. Can bind different peptides containing allele-specific binding motifs, which are mainly defined by anchor residues at position 2 and 9. Allele B*07:02: Displays peptides sharing a common signature motif, namely a Pro residue at position 2 and mainly a Leu anchor residue at the C-terminus. Presents a long peptide (APRGPHGGAASGL) derived from the cancer-testis antigen CTAG1A/NY-ESO-1, eliciting a polyclonal CD8-positive T cell response against tumor cells. Presents viral epitopes derived from HIV-1 gag-pol (TPQDLNTML) and Nef (RPQVPLRPM). Presents an immunodominant epitope derived from SARS-CoV-2 N/nucleoprotein (SPRWYFYYL). Displays self-peptides including a peptide derived from the signal sequence of HLA-DPB1 (APRTVALTA). Allele B*08:01: Presents to CD8-positive T cells viral epitopes derived from EBV/HHV-4 EBNA3 (QAKWRLQTL), eliciting cytotoxic T cell response. Allele B*13:02: Presents multiple HIV-1 epitopes derived from gag (RQANFLGKI, GQMREPRGSDI), nef (RQDILDLWI), gag-pol (RQYDQILIE, GQGQWTYQI) and rev (LQLPPLERL), all having in common a Gln residue at position 2 and mainly hydrophobic amino acids Leu, Ile or Val at the C-terminus. Associated with successful control of HIV-1 infection. Allele B*18:01: Preferentially presents octameric and nonameric peptides sharing a common motif, namely a Glu at position 2 and Phe or Tyr anchor residues at the C-terminus. Presents an EBV/HHV-4 epitope derived from BZLF1 (SELEIKRY). May present to CD8-positive T cells an antigenic peptide derived from MAGEA3 (MEVDPIGHLY), triggering an anti-tumor immune response. May display a broad repertoire of self-peptides with a preference for peptides derived from RNA-binding proteins. Allele B*27:05: Presents to CD8-positive T cells immunodominant viral epitopes derived from HCV POLG (ARMILMTHF), HIV-1 gag (KRWIILGLNK), IAV NP (SRYWAIRTR), SARS-CoV-2 N/nucleoprotein (QRNAPRITF), EBV/HHV-4 EBNA4 (HRCQAIRKK) and EBV/HHV-4 EBNA6 (RRIYDLIEL), conferring longterm protection against viral infection. Can present self-peptides derived from cytosolic and nuclear proteins. All peptides carry an Arg at position 2. The peptide-bound form interacts with NK cell inhibitory receptor KIR3DL1 and inhibits NK cell activation in a peptide-specific way, being particularly sensitive to the nature of the amino acid side chain at position 8 of the antigenic peptide. KIR3DL1 fails to recognize HLA-B*27:05 in complex with B2M and EBV/HHV-4 EBNA6 (RRIYDLIEL) peptide, which can lead to increased activation of NK cells during infection. May present an altered repertoire of peptides in the absence of TAP1-TAP2 and TAPBPL. Allele B*40:01: Presents immunodominant viral epitopes derived from EBV/HHV-4 LMP2 (IEDPPFNSL) and SARS-CoV-2 N/nucleoprotein (MEVTPSGTWL), triggering memory CD8-positive T cell response. Displays self-peptides sharing a signature motif, namely a Glu at position 2 and a Leu anchor residue at the C-terminus. Allele B*41:01: Displays self-peptides sharing a signature motif, namely a Glu at position 2 and Ala or Pro anchor residues at the C-terminus. Allele B*44:02: Presents immunodominant viral epitopes derived from EBV/HHV-4 EBNA4 (VEITPYKPTW) and EBNA6 (AEGGVGWRHW, EENLLDFVRF), triggering memory CD8-positive T cell response. Displays self-peptides sharing a signature motif, namely a Glu at position 2 and Phe, Tyr or Trp anchor residues at the C-terminus. Allele B*45:01: Displays self-peptides sharing a signature motif, namely a Glu at position 2 and Ala or Pro anchor residues at the C-terminus. Allele B*46:01: Preferentially presents nonameric peptides sharing a signature motif, namely Ala and Leu at position 2 and Tyr, Phe, Leu, or Met anchor residues at the C-terminus. The peptide-bound form interacts with KIR2DL3 and inhibits NK cell cytotoxic response in a peptide-specific way. Allele B*47:01: Displays self-peptides sharing a signature motif, namely an Asp at position 2 and Leu or Met anchor residues at the C-terminus. Allele B*49:01: Displays self-peptides sharing a signature motif, namely a Glu at position 2 and Ile or Val anchor residues at the C-terminus. Allele B*50:01: Displays self-peptides sharing a signature motif, namely a Glu at position 2 and Ala or Pro anchor residues at the C-terminus. Allele B*51:01: Presents an octameric HIV-1 epitope derived from gag-pol (TAFTIPSI) to the public TRAV17/TRBV7-3 TCR clonotype, strongly suppressing HIV-1 replication. Allele B*54:01: Displays peptides sharing a common signature motif, namely a Pro residue at position 2 and Ala anchor residue at the C-terminus. Allele B*55:01: Displays peptides sharing a common signature motif, namely a Pro residue at position 2 and Ala anchor residue at the C-terminus. Allele B*56:01: Displays peptides sharing a common signature motif, namely a Pro residue at position 2 and Ala anchor residue at the C-terminus. Allele B*57:01: The peptide-bound form recognizes KIR3DL1 and inhibits NK cell cytotoxic response. Presents HIV gag peptides (immunodominant KAFSPEVIPMF and subdominant KALGPAATL epitopes) predominantly to CD8-positive T cell clones expressing a TRAV41-containing TCR, triggering HLA-B-restricted T cell responses. Allele B*67:01: Displays peptides sharing a common signature motif, namely a Pro residue at position 2 and Leu anchor residue at the C-terminus.
Synonyms: HLAB; AS; B-4901
Tractability: Small molecule: a structure with a bound ligand is known. Antibody: UniProt places it where antibodies can reach, with high confidence; its Gene Ontology location is reachable by antibodies, with high confidence; UniProt predicts a signal peptide or a membrane-spanning region. PROTAC: ubiquitination databases record sites on it.
Target class: Surface antigen
Safety:
Unwanted effects reported when the protein is acted on. In parentheses: how it was acted on, where the effect was seen, and who reports it.
Severe Cutaneous Adverse Reactions, such as Stevens-Johnson Syndrome and Toxic Epidermal Necrolysis (source: ClinPGx)
Severe Cutaneous Adverse Reactions (source: ClinPGx)
adverse events (source: ClinPGx)
agranulocytosis (source: ClinPGx)
carbamazepine-induced adverse reactions (source: ClinPGx)
cutaneous adverse drug reactions (source: ClinPGx)
dapsone hypersensitivity syndrome or dapsone-induced severe cutaneous adverse reactions (source: ClinPGx)
dapsone-induced severe cutaneous adverse reactions (source: ClinPGx)
DRESS (source: ClinPGx)
DRESS Syndrome or SJS/TEN (source: ClinPGx)
hypersensitivity (source: ClinPGx)
hypersensitivity dermatitis (source: ClinPGx)
hypersensitivity reactions (source: ClinPGx)
liver injury (source: ClinPGx)
maculopapular eruption (source: ClinPGx)
maculopapular exanthema (source: ClinPGx)
nevirapine-related adverse events (source: ClinPGx)
respiratory failure (source: ClinPGx)
severe cutaneous adverse reactions (SCARs) (source: ClinPGx)
Severe Cutaneous Adverse Reactions, such as Stevens-Johnson Syndrome/Toxic Epidermal Necrolysis or drug reaction with eosinophilia and systemic symptoms (DRESS) (source: ClinPGx)
skin rash (source: ClinPGx)
Stevens-Johnson Syndrome (source: ClinPGx)
Stevens-Johnson syndrome/toxic epidermal necrolysis (SJS/TEN) (source: ClinPGx)
toxic liver disease (source: ClinPGx)
Gene: Protein-coding gene on chromosome 6 (31,353,867 to 31,367,067, reverse strand). Ensembl gene ENSG00000234745.
Subcellular location: Cell membrane; Endoplasmic reticulum membrane
Pathways (Reactome):
Immune System: Antigen Presentation: Folding, assembly and peptide loading of class I MHC; DAP12 interactions; ER-Phagosome pathway; Endosomal/Vacuolar pathway; Immunoregulatory interactions between a Lymphoid and a non-Lymphoid cell; Interferon alpha/beta signaling; Interferon gamma signaling; Neutrophil degranulation
Disease: SARS-CoV-2 activates/modulates innate and adaptive immune responses
Gene Ontology:
Molecular function: peptide antigen binding; protein binding; protein-folding chaperone binding; signaling receptor binding; TAP binding; beta-2-microglobulin binding
Biological process: antigen processing and presentation of endogenous peptide antigen via MHC class I via ER pathway, TAP-independent; antigen processing and presentation of exogenous peptide antigen via MHC class Ib; detection of bacterium; immune response; positive regulation of T cell mediated cytotoxicity; protection from natural killer cell mediated cytotoxicity; regulation of dendritic cell differentiation; regulation of interleukin-12 production; regulation of interleukin-6 production; regulation of T cell anergy; antigen processing and presentation of endogenous peptide antigen via MHC class Ib; defense response; regulation of natural killer cell mediated immunity; antigen processing and presentation
Cellular component: cell surface; endoplasmic reticulum; extracellular exosome; Golgi apparatus; membrane; MHC class I protein complex; MHC class Ib protein complex; plasma membrane; early endosome membrane; ER to Golgi transport vesicle membrane; external side of plasma membrane; Golgi membrane; lumenal side of endoplasmic reticulum membrane; phagocytic vesicle membrane; recycling endosome membrane; secretory granule membrane; endoplasmic reticulum membrane
Genetic constraint (gnomAD): Loss-of-function variants: 10 observed, 8.12 expected, observed/expected ratio (o/e) 1.23, 90% interval 0.75 to 1.85. That is too few expected variants to judge how well the gene tolerates losing a copy. Missense variants: 109 observed, 90.07 expected, observed/expected ratio (o/e) 1.21, 90% interval 1.03 to 1.42. Synonymous variants: 35 observed, 25.83 expected, observed/expected ratio (o/e) 1.35, 90% interval 1.03 to 1.77.
Homologues: Orthologues: macaque Mamu-B (78% identical), zebrafish si:ch211-147g22.4 (17% identical), zebrafish mhc1lia (14% identical). Paralogues in human: HLA-C (86% identical), HLA-A (85% identical), HLA-F (77% identical), HLA-E (76% identical), HLA-G (75% identical), MR1 (35% identical), HFE (34% identical), AZGP1 (29% identical), FCGRT (28% identical), MICB (27% identical), MICA (25% identical), CD1B (23% identical), and 10 more.
Diseases named in the same sentence as HLA-B in open-access papers:
HLA-B is named in the same sentence as 408 diseases in open-access papers, as found by Europe PMC text mining. Sharing a sentence is not in itself a finding about the gene and the disease. The quoted sentences say what the papers report.
AIDS (117 papers, 2006 to 2025). A syndrome resulting from the acquired deficiency of cellular immunity caused by the human immunodeficiency virus (HIV). "For example, HLA-B alleles are known to have strong influences on acquired immunodeficiency syndrome progression, where several HLA-B alleles, such as HLA-B∗57 and HLA-B∗27, are protective in HIV infections, whereas other alleles, such as HLA-B∗35, are linked to rapid progression." (PMID 40113210, 2025). "However, accurate imputation of HLA-B alleles is important, as they play a crucial role in the progression of acquired immune deficiency syndrome." (PMID 37768905, 2023). "For example, the activating KIR KIR3DS1, in combination with HLA-B alleles that encode molecules with isoleucine at position 80 (HLA-B Bw4-80Ile), is associated with delayed progression to AIDS following HIV infection." (PMID 40732677, 2025). "From a clinical point of view, the presence of both CCR5-Δ32 and HLA-B*57:01 have been associated with slow progression to AIDS in carrier individuals." (PMID 40858554, 2025). "Some variants of human leukocyte antigens (HLAs) are associated with a low viral load and slow progression to AIDS (HLA-B*57 and HLA-B*27), while the HLA-B*35 variant is associated with rapid progression." (PMID 36902388, 2023). "The expression of “protective” HLA-I alleles such as HLA-B*27, HLA-B*57, HLA-B*58:01, HLA-B*81:01 and HLA-A*74 is associated with low viral loads and slower progression to AIDS." (PMID 37267224, 2023). "Another study examined 96 HLA-A, B and C alleles for tapasin-dependence, showing large differences and finding that HIV progression to AIDS was slowest for tapasin-independent HLA-B alleles, as long as elite controllers were removed from the analysis." (PMID 35967451, 2022). "The interactions between NK cell receptors (KIR3DL1 and KIR3DS1) and the protective HLA-B Bw4-80Ile on target cells are associated with delayed progression to AIDS has been documented." (PMID 35911681, 2022). "In another study in human immunodeficiency virus (HIV) infected patients, the progression to AIDS was associated with the presence of HLA-B*35-HLA-Cw4 haplotype due to reduction of natural killer cell number and activity." (PMID 35252226, 2022). "For example, in HIV and AIDS, single nucleotide polymorphisms (SNP) in HLA-C, HLA-B and HCP5 genes were associated with high viral load at set point." (PMID 35252226, 2022). "HLA-B*81:01 is associated with slow progression to AIDS in African populations infected with HIV-1 subtype C strains and the second strongest protective allele in southern Africa (6, 30, 58, –, 60)." (PMID 36326273, 2022). "It has been reported that during HIV-1 infection, the activating receptor-encoding KIR allele KIR3DS1, in combination with HLA-B alleles encoding an isoleucine at position 80 (HLA-B Bw4-80Ile), was associated with delayed progression to AIDS." (PMID 35069597, 2021). "For example, HLA-B*27 and B-*57 alleles are associated with slower progression to AIDS and are highly enriched in a rare group of HIV-infected individuals called Long-term nonprogressors (LTNPs)." (PMID 32760139, 2020). "HLA-B*57, HLA-B*27, and HLA-B*52 are associated with a slow progression to AIDS (26, 27, 31, 33, –, 36), whereas HLA-B*35, HLA-B*58:02, and HLA-A*29:01-B*07:05-C*15:05 are associated with a rapid progression (28, 32, 34, 37, –, 40)." (PMID 32699092, 2020). "For example, the presence of protective HLA alleles, such as HLA-B*57 and HLA-B*27, is associated with lower viral loads and slower progression to AIDS, whereas the HLA-B*35 allele is associated with rapid progression to the disease." (PMID 32711474, 2020). "The transmission recipient, R097, expressed both HLA-B*27:05 and HLA-B*57:01, both of which are strongly associated with slow progression to AIDS." (PMID 29338738, 2018).
AIDS (continued). "In general, HLA molecules associated with more rapid progression to AIDS, such as HLA-B*18:01, HLA-B*35:01, and HLA-B*58:02, show dominant responses directed at non-Gag epitopes such as Nef or Env (16, 24, 33, –, 35)." (PMID 29167337, 2018). "Loss of immune control and progression to AIDS in HIV-infected HLA-B*27:05-positive individuals appeared to be precipitated by selection of an escape mutation at Gag residue 264, most commonly R264K or R264G (5, –, 7)." (PMID 29167337, 2018). "Located in the HLA complex P5 (HCP5), rs2395029 is a proxy for the HLA-B*57:01 allele, the strongest protective allele against AIDS progression." (PMID 28449694, 2017). "Genetic screening for HLA-B*57:01 and subsequent treatment modifications have been shown to reduce incidence of life-threatening hypersensitivity to abacavir in HIV/AIDS patients carrying the allele and HLA-B*15:02 to carbamazepine in Southeast Asian carriers." (PMID 28289388, 2017). "In HIV-1 infection, HLA-B alleles containing a Bw4 motif are associated with protection from AIDS and all HLA-Bw4 alleles (with the exception of HLA-B*38:01) encode for the −21T polymorphism, whereas HLA-Bw6 alleles encode for either −21T or −21M." (PMID 29184550, 2017). "Human alleles HLA-B*57, B*27, or B*53 are associated with an increased protection against AIDS or malaria, respectively, whereas the allele HLA-B*35 was linked to rapid progression to AIDS after HIV infection." (PMID 28623392, 2017). "In particular, studies in patients with HIV (human immunodeficiency virus) infection from different geographical areas have shown a correlation between HLA-B*35 phenotype and progression of AIDS (Acquired Immune Deficiency Syndrome)." (PMID 26669670, 2015). "For HIV-1-infected individuals, HLA-B*57:01 provides protection being strongly associated with reduced VL and delayed progression to AIDS." (PMID 26020813, 2015). "Typically, progression to a CD4 count of <200 cell/mm3 or AIDS appears to require the mutation at Arg-264 which abrogates binding of KK10 to HLA-B*27, and therefore would abolish the CD8+ T-cell response altogether, whereas L268X merely reduces recognition." (PMID 26834742, 2015). "As evidenced by the HIV example, several HLA-B alleles have been associated with control of viremia yet some individuals with these protective alleles develop AIDS (fail to control the virus)." (PMID 26347896, 2015). "Epidemiological studies have found that several 3DL1 homozygous genotypes co-carried with a subset of HLA-B and –A alleles belonging to the HLA-Bw4 group are associated with slower time to AIDS and viral load (VL) control." (PMID 24453969, 2014). "KIR3DL1/3DS1 in combination with HLA-Bw4-80I allotypes (in particular HLA-B*57) are associated with slow progression to AIDS in human HIV infection." (PMID 25506344, 2014). "In patients expressing 80I isoforms of HLA-Bw4, KIR3DL1-high is associated with delayed AIDS onset compared with other isoforms of HLA-B." (PMID 24919192, 2014). "HLA-B*51:01 is associated with slow progression to AIDS, and B51-TI8–specific T cells strongly suppress HIV-1 replication in vitro." (PMID 24600035, 2014). "Even when several HLA alleles were associated with disease progression, HLA-B*27 and HLA-B*57 alleles showed a particularly strong association with delayed progression and HLA-B*35 and HLA-B*53 with acceleration to AIDS." (PMID 25406087, 2014). "Nevertheless, genetic evidence suggests that HIV+ subjects with the activating KIR allele KIR3DS1, in combination with HLA-B alleles that encode molecules with isoleucine at position 80 (HLA-B Bw4-80Ile), have delayed progression to AIDS." (PMID 23630526, 2013). "The interaction of KIR3DS1 with HLA-B alleles that encode molecules with isoleucine at position 80 (HLA-B Bw4-80Ile) resulted in delayed progression of HIV infection to AIDS." (PMID 23950760, 2013).